GAPVD1 (GTPase activating protein and VPS9 domains 1)
Description:
Acts both as a GTPase-activating protein (GAP) and a guanine nucleotide exchange factor (GEF), and participates in various processes such as endocytosis, insulin receptor internalization or LC2A4/GLUT4 trafficking. Acts as a GEF for the Ras-related protein RAB31 by exchanging bound GDP for free GTP, leading to regulate LC2A4/GLUT4 trafficking. In the absence of insulin, it maintains RAB31 in an active state and promotes a futile cycle between LC2A4/GLUT4 storage vesicles and early endosomes, retaining LC2A4/GLUT4 inside the cells. Upon insulin stimulation, it is translocated to the plasma membrane, releasing LC2A4/GLUT4 from intracellular storage vesicles. Also involved in EGFR trafficking and degradation, possibly by promoting EGFR ubiquitination and subsequent degradation by the proteasome. Has GEF activity for Rab5 and GAP activity for Ras.
Synonyms: GAPEX5; KIAA1521; RAP6; DKFZP434C212; GAPex-5
Tractability: Antibody: UniProt places it where antibodies can reach, with high confidence; its Gene Ontology location is reachable by antibodies, with high confidence; the Human Protein Atlas places it where antibodies can reach. PROTAC: ubiquitination databases record sites on it; its protein half-life has been measured.
Gene: Protein-coding gene on chromosome 9 (125,261,780 to 125,367,207, forward strand). Ensembl gene ENSG00000165219.
Subcellular location: Membrane; Endosome
Subcellular location (Human Protein Atlas): Plasma membrane; Cytosol
Pathways (Reactome):
Vesicle-mediated transport: Clathrin-mediated endocytosis; RAB GEFs exchange GTP for GDP on RABs
Gene Ontology:
Molecular function: cadherin binding; GTPase activating protein binding; guanyl-nucleotide exchange factor activity; protein binding; small GTPase binding
Biological process: regulation of protein transport; vesicle-mediated transport
Cellular component: cytosol; plasma membrane; endocytic vesicle; endosome; membrane
Genetic constraint (gnomAD): Loss-of-function variants: 16 observed, 71.56 expected, observed/expected ratio (o/e) 0.22, 90% interval 0.15 to 0.34. The upper end of that interval is the gene's LOEUF score, 0.34, which puts it in group 1 of 6, group 1 being the genes least tolerant of losing a copy. Missense variants: 817 observed, 1,027 expected, observed/expected ratio (o/e) 0.8, 90% interval 0.75 to 0.84. Synonymous variants: 366 observed, 373.92 expected, observed/expected ratio (o/e) 0.98, 90% interval 0.9 to 1.07.
Homologues: Orthologues: chimpanzee GAPVD1 (99% identical), macaque GAPVD1 (99% identical), pig GAPVD1 (99% identical), dog GAPVD1 (99% identical), rabbit GAPVD1 (99% identical), guinea pig GAPVD1 (99% identical), mouse Gapvd1 (98% identical), rat Gapvd1 (97% identical), tropical clawed frog gapvd1 (87% identical), Drosophila melanogaster Gapvd1 (30% identical), zebrafish gapvd1 (28% identical), Caenorhabditis elegans rme-6 (20% identical). Paralogues in human: RIN3 (10% identical), RIN2 (10% identical), RIN1 (9% identical), VPS9D1 (7% identical), RINL (6% identical), RABGEF1 (5% identical).
Diseases named in the same sentence as GAPVD1 in open-access papers:
GAPVD1 is named in the same sentence as 7 diseases in open-access papers, as found by Europe PMC text mining. Sharing a sentence is not in itself a finding about the gene and the disease. The quoted sentences say what the papers report.
breast carcinoma (3 papers, 2014 to 2024). "Mutations in GAPVD1 and other genes, estrogen- and growth factor-dependent regulation are involved in both transcriptional and post-transcriptional dysregulation of syndecan-4 in breast cancer." (PMID 36499305, 2022). "We next analyzed GAPVD1 expression in human breast cancer via the TCGA and HPA databases." (PMID 38169627, 2024).
nephrotic syndrome (3 papers, 2020 to 2025). A collection of symptoms that include severe edema, proteinuria, and hypoalbuminemia; it is indicative of renal dysfunction. "Examples include mutations in the genes GTPase activating protein and VPS9 domains 1 (GAPVD1) and ankyrin repeat and FYVE domain containing 1 (ANKFY1) which were identified to cause a recessive type of nephrotic syndrome by impairing nephrin trafficking." (PMID 32708597, 2020).
osteosarcoma (1 paper, 2021). A usually aggressive malignant bone-forming mesenchymal neoplasm, predominantly affecting adolescents and young adults. "Moreover, in synchronized human U2OS osteosarcoma cells, which, in contrast to HeLa and HT1080 cells, possess a functional circadian oscillator, GAPVD1 was rhythmically associated with CSNK1D, and the strength of this interaction mirrored the binding of PER2 to CSNK1D." (PMID 33917494, 2021).
tumor (2 papers, 2024 to 2026). "NDRG1 contributes to tumor aggressiveness by cell proliferation and lipid metabolism regulation, whereas GAPVD1, INPP5A, TCN1, SAV1, RBBP8, SPIB, and UBE2A also exhibit oncogenic or tumor-suppressive properties associated with prognosis." (PMID 41511940, 2026). "Next, we assessed the effect of tumor growth and stem cell phenotype in vivo after GAPVD1 blockade." (PMID 38169627, 2024). "Knockdown of GAPVD1 significantly attenuated tumor growth in NOD/SCID mice." (PMID 38169627, 2024). "High GAPVD1 and NRP-1 expression correlated with lymph node metastasis and tumor size in TNBC." (PMID 38169627, 2024). "In addition, we also demonstrated that knockdown of GAPVD1 significantly attenuated tumor growth in NOD/SCID mice in vivo and that GAPVD1 expression indicated poor prognosis in TNBC specimens." (PMID 38169627, 2024).
cancer (1 paper, 2024). A tumor composed of atypical neoplastic, often pleomorphic cells that invade other tissues. "Our study underscores the crosstalk between TNBC cells and TAMs mediated by VEGFA and further clarifies the role and underlying mechanisms of the VEGFA/NRP-1/GAPVD1 axis in regulating cancer stemness." (PMID 38169627, 2024). "Above all, our data support and broaden the concept that the VEGFA/NRP-1/GAPVD1 axis targets the downstream Wnt/β-catenin signaling pathway in regulating cancer stemness in TNBC cells." (PMID 38169627, 2024). "GAPVD1 was previously reported as a GTPase regulator, but the precise mechanism of cancer stemness in TNBC cells remains unclear." (PMID 38169627, 2024). "TAM-derived VEGFA may promote cancer stemness of TNBC through the NRP-1/GAPVD1/Wnt/β-catenin axis in an autocrine and paracrine manner." (PMID 38169627, 2024). "Our present results showed that VEGFA produced by TAMs promoted the cancer stemness of TNBC cells via the NRP-1 receptor and the downstream GAPVD1/Wnt/β-catenin signaling pathway." (PMID 38169627, 2024). "Collectively, these data showed that the VEGFA/NRP-1/GAPVD1 axis is involved in the regulation of cancer stemness and mobility in TNBC cells and that GAPVD1 acts as an effector downstream of NRP-1 in this process." (PMID 38169627, 2024). "As to VEGFA, we showed that VEGFA produced by TAMs promoted the cancer stemness of TNBC cells via the NRP-1 receptor and downstream GAPVD1/Wnt/β-catenin signaling pathway." (PMID 38169627, 2024). "VEGFA maintains cancer stemness and progression of TNBC through the NRP-1/GAPVD1 axis and Wnt/β-catenin signaling pathway." (PMID 38169627, 2024).
GAPVD1 also shares sentences with these, for which no sentence is quoted: autism spectrum disorder (1 paper); triple-negative breast carcinoma (1).